NOTCH1 (notch receptor 1)
Diseases named in the same sentence as NOTCH1 in open-access papers (continued):
Sharing a sentence is not in itself a finding about the gene and the disease.
tumor (continued). "In addition to alteration in cell proliferation, our GSEA analysis demonstrated that inhibition of KDM2A attenuates tumor angiogenesis and mRNA expression of several genes in the NOTCH signaling pathway including JAG1, NOTCH1, HEY1." (PMID 27029061, 2016). "Our data indicated that Notch-1 gene was significantly down-regulated (log2 (Ratio) = −1.3895) in K1-CXCR7 cell, which suggested Notch-1 gene might have the effect of tumor suppression in PTC." (PMID 25887589, 2015). "Moreover, by up-regulation of Notch1 and VEGFR1, DLL4 played important roles in tumor angiogenesis and prognosis of lung cancer." (PMID 25996086, 2015). "Further, in the tumor-draining LN (TDLN), tumor-specific Vβ8.1/2+ CD8+ T cells representing a frequency of 8-10% (data not shown) showed increased expression of the surface receptor and mRNA of Notch1 and Notch2 following bortezomib treatment." (PMID 26431276, 2015). "Activated Notch1 and HES1 were also overexpressed in the cytoplasm and nuclei of PDAC tumor cells." (PMID 25483102, 2015). "Moreover, in endothelial and tumor cells' coculture model, it was shown that the expression of a NOTCH ligand DLL4 (Delta-like ligand 4) in HUVEC endothelial cells increased NOTCH1 and suppressed the proliferation of cocultured A549 and H460 NSCLC cells." (PMID 26491213, 2015). "EGFR is involved in the tumor angiogenesis of HNSCC via the HIF-1α and Notch1 pathways." (PMID 25723392, 2015). "STAT3 signaling has also been widely implicated in tumor progression and tumor cell stemness, not least through induction of HIF-1α and Notch1." (PMID 26343197, 2015). "Analysis of disease-related clinicopathological parameters showed neither a significant association between Notch1 expression and demographics including age and sex, nor a correlation between Notch1 and tumor grade or tumor size." (PMID 25653136, 2015). "Nevertheless, in conclusion and to the best of our knowledge, our study showed for the first time a close relationship of a decrease of NOTCH1 and NOTCH2 expression with tumor progression in GC, and our findings suggested that, in particular, NOTCH1 expression was a marker for good prognosis." (PMID 25954607, 2015). "The close relationship of high NOTCH1 and NOTCH2 expression with early tumor stages may indicate a tumor-suppressive role of NOTCH signaling in GC." (PMID 25954607, 2015). "Secondly, other lines of experimental evidence showed that without Notch1 activation, the adherens junctions complex containing E-cadherin is intact, which suppresses tumor cell migration and metastasis." (PMID 25653136, 2015). "Additionally, Western blot analysis of tumor tissue samples found that tetrandrine increased LC3-II protein levels and activated the Notch1 signaling pathway." (PMID 25797266, 2015). "In addition, the density of tumor microvessels (PECAM+) in the visfatin siRNA-transfected and Notch1 siRNA-transfected groups was dramatically lower than that in the control group." (PMID 24970818, 2014). "In addition to downregulation, we frequently observed delocalization of NOTCH1 and DLL1 to the cytoplasm in tumour cells." (PMID 25167871, 2014). "NOTCH1 and its ligand, DLL1, were expressed at plasma membranes and in the cytoplasm of cells in the upper normal urothelium layer, but became downregulated in UC tissues, especially in high-stage tumours." (PMID 25167871, 2014). "Taken together, these results suggest that what were previously called osteoclast-like multinucleated giant cells are not osteoclasts, but rather angiogenic tumor cells that involve ADAM10/Notch1 signaling activation." (PMID 24548763, 2014). "For example, while Notch1 is often oncogenic when expressed by cancer cells, Notch3 expressed by perivascular cells plays a major role in JAG1-mediated vascular function, and it is also important in Treg induction and expansion in the tumor microenvironment." (PMID 25309874, 2014).
tumor (continued). "Tumor tissues were then embedded in paraffin, stained with hematoxylin and eosin (H&E), and immunohistochemically stained with antibodies against FOXA1, AR, Notch1, Hes1, Ki67, or PCNA." (PMID 24512546, 2014). "The mechanisms by which miR-139-5p acts as a tumor suppressor in CRC involve inhibition of cell proliferation and metastasis, and induction of G0/G1 arrest and apoptosis through repression of oncogenic NOTCH1." (PMID 24885920, 2014). "Notch1 and Notch4 have been reported to have higher activity in the enriched breast CSC population, and inhibition of Notch signaling reduced stem cell activity in vitro and tumor formation in vivo." (PMID 25309874, 2014). "The expression of Notch1 and Jagged1 proteins was detected to be higher in tumor tissues than in non-neoplastic tissues by western blot analysis." (PMID 24959218, 2014). "A remarkable reduction in tumor weight and volume but not in body weight was observed in mice injected with visfatin or Notch1 siRNA-transfected cells." (PMID 24970818, 2014). "Reverse transcriptase - quantitative PCR (RT-qPCR) was utilized to quantify HES1, HEY1, NOTCH1 and NOTCH2 gene expression in matched tumor and normal metaphyseal bone samples taken from dogs treated for appendicular OSA at the Colorado State University Veterinary Teaching Hospital." (PMID 23816051, 2013). "Collectively, these results indicate that NOTCH1 activation could induce EMT in epithelial tumor cells and, consequently, to favor tumor metastasis." (PMID 23826634, 2013). "In conclusion, we have shown here that Notch1 expression is upregulated in clinical ICC specimens and promotes tumor migration, indicating that Notch1 may be involved in ICC carcinogenesis and progression." (PMID 23688168, 2013). "In fact, regardless of the tumor cell type, NOTCH1 strongly labeled the mitochondria, with preferential localization along the mitochondrial membranes." (PMID 23955600, 2013). "We further revealed that AQP3 was a transcriptional target of Notch signaling, a critical pathway regulating keratinocyte differentiation and tumor suppression, and it regulated differentiation through a reciprocal negative feedback loop with Notch1." (PMID 24260356, 2013). "To further investigate whether PTE or/and DAPT regulates Notch1 signaling in vivo, we examined NICD and Hes1 expression in tumor tissues." (PMID 23671619, 2013). "Other groups have shown that antibodies against Dll4 and Notch1 increase non-functional EC vasculature in subcutaneous tumor models." (PMID 24066611, 2013). "Nuclear Notch1, indicative of pathway activation, was not identified in normal ducts, but occurred in tumours of 11 patients with resected PDAC (26.2%, p<0.001)." (PMID 23226563, 2012). "Notch signalling mediated the tumour-initiating effects of TGF-α by expanding a population of undifferentiated precursor cells and in human PDAC, up-regulation of Notch1, and -4 and Jagged-1 and -2 proteins in resected specimens, as well as PanIN lesions, was observed." (PMID 23226563, 2012). "Notch1 expression was positive correlated with tumor diameter (n = 23, R = 0.435, P = 0.038) while Jagged1 expression was not significantly correlated with tumor size (n = 23, R = −0.172, P = 0.432)." (PMID 22506064, 2012). "Notch1 expression was positive correlated with tumor diameter while Jagged1 expression had no significantly correlation with tumor size." (PMID 22506064, 2012). "We found out that Notch1 and Jagged1 expression was significantly elevated in both localized and metastatic tumor tissues compared to non-tumor tissues." (PMID 22506064, 2012). "Conversely, Notch1 was expressed in the vasculature within the tumor mass but not in malignant cells." (PMID 22074495, 2011). "Taken together, our findings confer that Notch1, but not Notch2 is a tumor suppressor and plays a crucial role in proper skin development and differentiation." (PMID 21042537, 2010).
tumor (continued). "Until recently, methods for the delivery of activated Notch1 to tumor cells, aside from gene therapy, had been nonexistent." (PMID 20069043, 2009). "Notch-1 expression increased significantly in the six-week developing tumor, but not in the established 16-week tumor, suggesting an early role in the dynamics of epithelial proliferation and differentiation prior to the appearance of histologic changes." (PMID 17343742, 2007). "For example, IC1 – IC3 and IC6 overlapped with molecular subtype A (standardised residuals 2:4 each), which is characterised by a high proportion of mutations in driver genes such as NOTCH1 and RREB1 (with or without BICRA and MIDEAS mutations) and was found mostly in benign dMMR tumours." (PMID 41419736, 2025). "By activating downstream target genes such as HES and HEY families, NOTCH1 modulates key biological processes, including tumor cell proliferation, apoptosis, angiogenesis, and TME remodeling, thereby exerting a profound impact on tumor biological behavior and treatment sensitivity." (PMID 41306984, 2025). "Using these five sites on FZD10 and NOTCH1 as criteria, the high-difference change group exhibited a significantly better prognosis than the low-difference (shallow) change group, indicating a negative impact of the tumor on surrounding tissue." (PMID 41184502, 2025). "Finally, this study suggests a possible cross-talk between Notch1 and CD10 expression that may drive tumor aggressiveness and treatment resistance." (PMID 40060224, 2025). "Investigation on Notch1 and CD10 expression in tumor may help predicting drug resistance." (PMID 40060224, 2025). "Our tumor driver screening also supports this hypothesis since constitutive activity of well-known factors of CLL disease progression, such as PI3K/AKT, MAPK, or NOTCH1 activation, combined with BMI1 activity, led to a proliferative attractor." (PMID 40938978, 2025). "However, the exact mechanisms that govern the tumor suppressive role of Notch1 in this context are not yet fully understood." (PMID 39063983, 2024). "Genomic profiling revealed no actionable targets but NOTCH1 and KDM6A frameshift and CTCF splice site mutations (no MYB/L fusion) with a low tumor mutational burden (TMB), microsatellite stable (MSS) and negative programmed death ligand 1 (PD-L1) were observed." (PMID 39451738, 2024). "Repression of endothelial Snai1-expression in the strongly pro-angiogenic tumor microenvironment has the opposite effect, reducing the ill-fated excessive sprouting via increased Notch1/Dll4 expression, leading to stable vessels that are no longer prone to constant remodeling and degradation." (PMID 39095583, 2024). "Interestingly, it has been described that some malignancies, SCLC cells, and tumor tissues do not express Notch1 protein." (PMID 40034926, 2024). "We were not able to directly confirm Notch1/2 deletion in end-stage tumours." (PMID 37686600, 2023). "Next, we examined whether overactivation of AT-EC Notch1 signaling could alone (that is, without the presence of a tumor) induce adipose tissue remodeling as usually seen in cancer cachexia." (PMID 37749321, 2023). "Mechanistically, Notch1 signaling does not directly increase MenaINV expression, but it enhances and sustains NF-κB signaling through retention of p65, an NF-κB transcription factor, in the nucleus of tumor cells, leading to increased MenaINV expression." (PMID 37024946, 2023). "Indeed, in a similar manner to pluripotent cells, disparities of Notch activation have been observed between cells populating the edge of the tumor, with low signs of NOTCH activation, and cells originating from the center, with a high expression of NOTCH1 ICD." (PMID 37860822, 2023). "Moreover, Notch 1 and Notch 2 appear to have opposite functions in embryonic brain tumors and pancreatic ductal adenocarcinoma (PADC), adding another layer of complexity on the role of Notch signaling in tumor progression." (PMID 37255594, 2023).
tumor (continued). "Additionally, an in vitro study on breast cancer showed that luteolin, by interfering with Notch1 expression, inhibited VEGF secretion from tumor cells, decreased endothelial cell migration, proliferation, and their propension to form tube-like structures on a Matrigel layer." (PMID 37240168, 2023). "In the present study, we found that overexpressed TRAF3IP2 in NONO-TFE3 tRCC could enhance tumor progression through function as a co-activator of NOTCH1 to mediate NOTCH1 target genes." (PMID 35897085, 2022). "Some authors suggested that Notch1 could act as a tumor suppressor, whereas others reported Notch as a driver for hepatocyte dedifferentiation and tumor progression." (PMID 35805898, 2022). "Our study also demonstrated that increased expression of TDP43 controlled by lncRNA LCETRL3 could stabilize the NOTCH1 mRNA, elevate NOTCH1 expression, downregulate PTEN expression and activate AKT in NSCLC cells, which thereby accelerating tumor growth and reduce EGFR-TKIs efficiency." (PMID 35095099, 2022). "miR-34a directly targets the 3’UTRs of numerous oncogenic mRNAs, including ARAF, CD44, CD117, CDK4, c-Met, cyclin D3, cyclin E2, E2F3, Fra-1, Jagged1, MCM2/5, MET, MYCN, Notch1/2, PIK3R2, PLK1, Smad4, SIRT1/6, and VEGFA, which may contribute to its tumor-suppressive role." (PMID 35961977, 2022). "Silencing Notch1 signaling or HIF-1α inhibition showed a notable anti-growth effect in early treatment with doxycycline or chetomin, indicating that HIF-1α might be a promising therapeutic target even in an early stage of tumor progression." (PMID 36183290, 2022). "In addition, we found that the expressions of FOXM1, ADAM17, NOTCH1 and N-cadherin were decreased in SPAG5-downregulated tumor tissues, while E-cadherin expression was increased, highlighting the role of SPAG5 in downregulation of the expression of FOXM1, ADAM17 and NOTCH1, and inhibiting EMT." (PMID 35138218, 2022). "However, NOTCH-1 and NOTCH-3 were positively correlated with the tumor grade and stage." (PMID 36476410, 2022). "The loss of Notch1 combined with oncogenic Hras expression induced formation of aggressive tumors, whereas oncogenic HRAS expression alone resulted in small tumors or no tumors at all in a xenograft tumor model." (PMID 34572732, 2021). "In addition, it could inhibit the migration of tumor cells via the downregulation of MMP-9 and Notch-1 level." (PMID 34443415, 2021). "Interestingly, it has been observed that NOTCH1 controls NOTCH2, thus acting as a tumor suppressor." (PMID 34446793, 2021). "At the same time, overexpression of miR-760, normally suppressed by doxorubicin treatment, mitigated HCC resistance to this chemotherapeutic drug through inhibiting Notch1 and promoting PTEN expression, demonstrating that inhibition of Notch1 might be re-sensitizing in this tumor as well." (PMID 34680255, 2021). "Despite identifying upregulation of Notch-1 signaling, which increased up to 40 times in some patients, no overall tumour regression was seen in any patient, suggesting augmentation of this pathway may have only limited effects." (PMID 34439335, 2021). "Using RBPj-Notch reporter activation as an indicator for Notch activation and combining with specific Notch receptor antagonists, it was found that this effect proceeded from endothelial Dll4 signaling through Notch1, but not Notch3, in neighboring tumor cells." (PMID 33198378, 2020). "Multiple authors have reported that blocking NOTCH1 function with shRNA leads to a decrease in HNSCC tumor spheroid growth in three-dimensional (3-D) cultures, and conversely expression of ICN1 can increase survival and growth of spheroids or enhance tumor growth in mice." (PMID 33322834, 2020). "In addition, immunohistochemical staining revealed overexpression of NOTCH1 in both PDX and tumor tissue, whereas no NOTCH1 immunoreactivity was detected in the surrounding normal tissue." (PMID 32042099, 2020).
tumor (continued). "Regardless of whether Notch signaling promotes T cells into effector cells or memory cells, Notch2 but not Notch1 signaling has been demonstrated to be essential for potent anti-tumor immunity." (PMID 33585446, 2020). "In order to determine the function of NOTCH1C1133Y mutation in tumor progression and metastasis, we first performed gain-of-function assays in HN6 and CAL27 cell lines that express a low range of endogenous NOTCH1 compared with other OSCC cell lines (data not shown)." (PMID 32792479, 2020). "Interestingly, tumor formation and growth rate were increased equivalently by the loss of either one or both NOTCH1 alleles when E6/E7 was present with KRASG12D; whereas loss of both NOTCH1 alleles was required to promote tumor growth when E6/E7 was absent." (PMID 33322834, 2020). "Even though the highly expressed miR-144-3p can inhibit the EMT of tumor tissues and cells by targeting EZH2, PBX3, and MAP3K8, we found that EMT could be negatively regulated by miR-144-3p through the ROS/NRF2/Notch1/Snail pathway in high-glucose-stimulated LECs." (PMID 33274006, 2020). "The activation of doxycycline-inducible NOTCH1 and NOTCH3 in TT cells, through treatment with increased doses of doxycycline, has demonstrated a dose-dependent increase in NOTCH1, NOTCH3 and HES1 protein, a decrease in ASCL1 levels and ultimately a reduction in tumour growth in vitro and in vivo." (PMID 31443481, 2019). "Importantly, we found that Notch1+ tumour cells do not coincide with CSCs expressing the Lgr5 receptor, while they share a transcriptional signature with normal ISCs." (PMID 30696875, 2019). "Overexpression of the NOTCH1 intracellular domain (NICD) in SJG6 cells promoted cell adhesion and differentiation, while suppressing proliferation, migration and clonal growth, consistent with the previously reported tumour suppressive function of NOTCH1 in OSCC." (PMID 31827722, 2019). "It should be noted that the Notch pathway results upregulated in the Lgr5hi tumour signature and not in our Notch1 dataset, since we have compared deregulated genes between Notch1+ normal crypt cells and Notch1+ tumour cells, both presenting activation of Notch signalling." (PMID 30696875, 2019). "Moreover, the expression of other histopathological parameters such as EGFR, VEGF, and NOTCH1 differ between p16 positive and negative tumors, which suggest differences in tumor angiogenesis in these entities." (PMID 30718984, 2019). "Furthermore, downregulation of the Notch1 pathway by shRNA and MK0752 significantly inhibited the PI3K/AKT/mTOR signaling pathway via the decreased expression of CXCR4 in GICs, and weakened the self-renewal, invasion and tumor growth ability of GICs." (PMID 31382985, 2019). "qRT-PCR analysis of these three FACS sorted populations showed that Notch1-derived lineages (in blue) express intermediate levels of both Lgr5 and differentiation markers, such as lysozyme, between non-labelled cells (in red) and Notch1-expressing tumour cells (in green)." (PMID 30696875, 2019). "However, the Wnt pathway is not significantly increased in the Notch1+ signature, suggesting that Notch1+ tumour cells do not present higher Wnt activity than Notch1+ ISCs and in agreement with reduced Lgr5 expression in these cells." (PMID 30696875, 2019). "In addition, Notch1+ tumour cells appear more proliferative than non-marked tumour cells, as shown by the significantly increased proportion of GFP+ cells in the S and G2/M phases of the cell cycle." (PMID 30696875, 2019).